MIR1302-1 (microRNA 1302-1)
Synonyms: hsa-mir-1302-1; MIRN1302-1
Gene: MicroRNA gene on chromosome 12 (112,695,034 to 112,695,176, reverse strand). Ensembl gene ENSG00000283507.
Homologues: Orthologues: chimpanzee ptr-mir-1302-1 (100% identical). Paralogues in human: MIR1302-8 (64% identical), MIR1302-6 (40% identical).